RPAP3 (RNA polymerase II associated protein 3)
Description:
Forms an interface between the RNA polymerase II enzyme and chaperone/scaffolding protein, suggesting that it is required to connect RNA polymerase II to regulators of protein complex formation.
Synonyms: FLJ21908; spag; hSpagh; Tah1
Tractability: Small molecule: a structure with a bound ligand is known. PROTAC: UniProt records ubiquitination sites on it; ubiquitination databases record sites on it; its protein half-life has been measured.
Gene: Protein-coding gene on chromosome 12 (47,661,249 to 47,706,038, reverse strand). Ensembl gene ENSG00000005175.
Subcellular location (Human Protein Atlas): Cytosol; Acrosome; Basal body; Primary cilium; Primary cilium tip
Gene Ontology:
Molecular function: protein binding
Biological process: protein stabilization
Cellular component: cytosol; R2TP complex; RPAP3/R2TP/prefoldin-like complex
Genetic constraint (gnomAD): Loss-of-function variants: 22 observed, 27.46 expected, observed/expected ratio (o/e) 0.8, 90% interval 0.57 to 1.14. The upper end of that interval is the gene's LOEUF score, 1.14, which puts it in group 5 of 6, group 1 being the genes least tolerant of losing a copy. Missense variants: 257 observed, 280.94 expected, observed/expected ratio (o/e) 0.91, 90% interval 0.82 to 1.01. Synonymous variants: 98 observed, 100.11 expected, observed/expected ratio (o/e) 0.98, 90% interval 0.83 to 1.16.
Homologues: Orthologues: chimpanzee RPAP3 (99% identical), macaque RPAP3 (97% identical), dog RPAP3 (89% identical), pig RPAP3 (89% identical), guinea pig RPAP3 (88% identical), mouse Rpap3 (79% identical), rat Rpap3 (78% identical), rabbit RPAP3 (76% identical), tropical clawed frog rpap3 (57% identical), zebrafish rpap3 (44% identical), Drosophila melanogaster spag (22% identical). Paralogues in human: SPAG1 (23% identical), STIP1 (15% identical), UNC45A (14% identical), TTC12 (14% identical), UNC45B (14% identical), TOMM34 (12% identical), TOMM70 (11% identical), ST13 (11% identical), SPATA16 (11% identical), TTC31 (10% identical), SUGT1 (10% identical), TTC1 (10% identical), and 6 more.
Diseases named in the same sentence as RPAP3 in open-access papers:
RPAP3 is named in the same sentence as 9 diseases in open-access papers, as found by Europe PMC text mining. Sharing a sentence is not in itself a finding about the gene and the disease. The quoted sentences say what the papers report.
breast carcinoma (1 paper, 2013). "Of these, we focused on amphiregulin, because its probe signal was markedly up-regulated both in RPAP3 and PIH1D1 siRNA-treated cells; moreover, amphiregulin has been reported to have high levels of expression in hormone therapy-resistant breast cancer cells." (PMID 23844004, 2013).
colorectal cancer (1 paper, 2021). A primary or metastatic malignant neoplasm that affects the colon or rectum. "In agreement with a link between R2TP and cell proliferation, we found that high RPAP3 expression in human colorectal cancer (CRC) tissues is associated with shorter disease-free survival (DFS) in patients." (PMID 34376666, 2021).
colorectal tumors (1 paper, 2021). "Here the authors report that deletion of Rpap3 abrogates cell proliferation and homeostasis in mouse intestine, partly through destabilization of PI3K-like kinases, while elevated RPAP3 levels in colorectal tumors are associated with poor prognosis." (PMID 34376666, 2021). "In addition, high RPAP3 levels in colorectal tumors from patients correlate with bad prognosis." (PMID 34376666, 2021).
mucinous carcinoma (1 paper, 2021). "Furthermore, compared with mucinous carcinoma, the expression of RPAP3 was increased in CRC of the adenocarcinoma type (p = 0.025)." (PMID 34376666, 2021).
viral infection (1 paper, 2019). "The effect of RPAP3 knockdown was assessed in the setting of multiple-round viral infection." (PMID 31121004, 2019). "Thus, for MuV, the effects of RPAP3 knockdown on multiple-round viral infection were consistent with the results of the one-step growth experiments until 48 hpi, but an additional mechanism was necessary to explain the data after 48 hpi." (PMID 31121004, 2019).
cancer (3 papers, 2020 to 2025). A tumor composed of atypical neoplastic, often pleomorphic cells that invade other tissues. "Dictyoceratin-C was found to target RNA polymerase II-associated protein 3 (RPAP3) and inhibit the growth of cancer cells selectively under hypoxic conditions." (PMID 35200628, 2022). "WAC expression was also correlated with that of RPAP3 and PIH1D1 (in three out of 10 cancer types), components of R2TP, and we also found some correlation with TTI2." (PMID 40653822, 2025).
tumor (1 paper, 2021). "The relationships between RPAP3 expression and clinico-pathological parameters were investigated by Pearson’s χ2 test: RPAP3 expression negatively correlated with the tumor stage of CRC (p = 0.049)." (PMID 34376666, 2021). "In addition, high RPAP3 expression was positively correlated with the occurrence of tumor relapse (p = 0.003) and patients’ mortality (p = 0.036)." (PMID 34376666, 2021).
RPAP3 also shares sentences with these, for which no sentence is quoted: adenocarcinoma (1 paper); ovarian carcinoma (1).